UHRF1 (ubiquitin like with PHD and ring finger domains 1)
Diseases named in the same sentence as UHRF1 in open-access papers (continued):
Sharing a sentence is not in itself a finding about the gene and the disease.
cancer (continued). "Altogether, these studies highlight UHRF1 as a conductor of tumor suppressor gene silencing in cancers through a DNA methylation-dependent mechanism." (PMID 28881702, 2017). "Specificity protein 1 (SP1) and Forkhead Box M1 (FOXM1) also potentiate UHRF1 expression in different cancers." (PMID 28881702, 2017). "Our finding that UHRF1/2 negatively regulates DNA methylation uncovers a mechanism for DNA hypomethylation in cancer." (PMID 27462454, 2016). "It appears that p16INK4A upregulation through a UHRF1 downregulation is a key mechanism of many natural drugs exhibiting anti-cancer properties." (PMID 27839516, 2016). "All these studies support the existence of a common mechanism in cancer that UHRF1 regulates the expression of p16INK4A with subsequent inhibition of the apoptotic pathways." (PMID 27839516, 2016). "UHRF1/2 are frequently overexpressed in cancers and we present evidence that UHRF1/2 overexpression downregulates DNMT3A proteins and consequently leads to DNA hypomethylation." (PMID 27462454, 2016). "Ablation of UHRF1 induces genomic hypomethylation, and overexpression of UHRF1 has been reported in several cancers." (PMID 27487138, 2016). "Altogether, our data, combined with existing evidence provides a basis for investigating UHRF1 as a possible therapeutic target in human cancer." (PMID 27431502, 2016). "UHRF1 is involved in a wide range of physiological and pathological phenomena, including cancer development and metastasis." (PMID 27072587, 2016). "UHRF1 was expressed moderately or strongly in several cancer lesions, and normal bladder tissues stained weakly." (PMID 27072587, 2016). "In this regard, UHRF1 overexpression is widespread in cancers, consistent with the previous reports that UHRF1 is overexpressed in various cancers including breast, prostate, lung, colorectal and bladder." (PMID 27462454, 2016). "UHRF1 mRNA expression levels were significantly higher in cancer tissues than in normal mucosa (P < 0.0001)." (PMID 27507047, 2016). "In this type of cancer, UHRF1 knockdown induced an upregulation of p16INK4A, inhibition of cell proliferation and metastasis as well as apoptosis." (PMID 27839516, 2016). "Silencing of UHRF1 induced apoptosis and inhibited cancer cell proliferation, migration, and invasion in BC cells." (PMID 27072587, 2016). "In vitro and in vivo studies have shown that a drug-induced inhibition of UHRF1 activity or expression leads to the reactivation of several tumor suppressor genes enabling cancer cells to undergo apoptosis." (PMID 27839516, 2016). "Several in vitro and in vivo works have reported the direct implication of the epigenetic player UHRF1 in tumorigenesis through the repression of TSGs expression and suggested UHRF1 as a promising target for cancer treatment." (PMID 27839516, 2016). "UHRF1 has been shown to be highly expressed in many cancers, and UHRF1 overexpression is mechanism of DNA hypomethylation in tumor cells." (PMID 27507047, 2016). "So, understanding the molecular mechanisms underlying UHRF1 overexpression in cancer will help to find new targets to inhibit UHRF1 expression which will allow cancer cells to undergo apoptosis through the reactivation of silenced TSGs." (PMID 27839516, 2016). "Up-regulation of UHRF1 has been observed in a variety of cancers and appears to serve as an independent prognostic factor." (PMID 27431502, 2016). "Expression of UHRF1 is upregulated in several cancers (e.g., breast, lung, pancreatic, and cervical cancers), suggesting that this protein is involved cancer development and progression." (PMID 26884069, 2016). "This suggests that defects in T3/TR pathway in cancer cells result in UHRF1 overexpression through increasing of Sp1 binding to its promoter with subsequent cell proliferation and metastasis." (PMID 27839516, 2016). "Intriguingly, many factors involved in the DDR are considered tumour suppressors, while UHRF1 is overexpressed in many cancers and considered oncogenic." (PMID 26727879, 2016).
cancer (continued). "All these findings indicate that UHRF1 is a main key in the epigenetic silencing of various TSGs in cancer." (PMID 27839516, 2016). "Accumulating evidence suggests that UHRF1 is overexpressed in human cancers and plays a crucial role in malignant tumor behavior." (PMID 27507047, 2016). "UHRF1 is particularly interesting in this context given its recent identification as an oncogene that drives DNA hypomethylation in cancer cells." (PMID 25889361, 2015). "This showed that those genomic loci whose DNAm levels correlated most strongly with increased gene expression of UHRF1 or WHSC1 were also significantly highly ranked in most other cancer types." (PMID 26169266, 2015). "UHRF1 is known to regulate gene expression and the cell cycle and is overexpressed in many cancers, and it is of note that UHFR1 binds inverted CCAAT motifs perhaps enabling requirement of FOXM1 at these specific genomic binding sites." (PMID 26100407, 2015). "UHRF1 is frequently overexpressed in various human tumors and has an important role in cancer pathogenesis and progression." (PMID 25765655, 2015). "To further delineate the expression levels of UHRF1 in different cancer tissues, we performed immunohistochemical analysis of a tissue array that contained both normal and cancerous tissues." (PMID 25765655, 2015). "In cancer cells, UHRF1 represses several tumor-suppressor genes including p16INK4A, hMLH1, p21 and RB." (PMID 25765655, 2015). "MiR-146a was shown to directly inhibit expression of UHRF1, an epigenetic regulator and coordinate tumor suppressor gene silencing via DNA methylation in several cancers." (PMID 25608619, 2015). "Our pan-cancer-wide analysis shows that expression of UHRF1 correlates consistently with DNA hypermethylation across samples of a given cancer type, while it did not do so with DNA hypomethylation." (PMID 26169266, 2015). "Our search of the Oncomine database found that UHRF1 was upregulated in various types of cancers compared with its expression in normal tissues." (PMID 25765655, 2015). "UHRF1 results in abnormal DNA methylation and cancer metastasis, and UHRF1 expression is correlated with a poor prognosis in several cancers." (PMID 25272010, 2014). "For instance, EZH2 and UHRF1 are two of the most frequently overexpressed chromatin factors but are rarely amplified in cancer." (PMID 25484917, 2014). "UHRF1 is upregulated in multiple types of cancers, and overexpression of UHRF1 is involved in tumorigenesis and cancer progression." (PMID 25272010, 2014). "In contrast to TET genes, both mRNA and protein expression levels of UHRF1 gene were highly upregulated in HCCs, consistent with previous reports in various types of cancers." (PMID 25517360, 2014). "Another E3 ligase that is frequently elevated in various cancers is UHRF1 (ubiquitin-like with PHD and RING finger domains)." (PMID 23730625, 2013). "In this context, recently we found that the epigallocatechin-3-gallate (EGCG), a natural anti-cancer drug induces G1 cell arrest and apoptosis in Jurkat cells by down-regulating UHRF1 and DNMT1 expression, with subsequent up-regulation of p16INK4A gene." (PMID 23688286, 2013). "UHRF1, a putative oncogenic factor, is over-expressed in numerous cancers and has been suggested to be an important biomarker to discriminate between cervical high-grade and low-grade cancer lesions." (PMID 21496237, 2011). "Several studies showed that down-regulation of UHRF1 expression in cancer cells by natural pharmacological active compounds, favors enhanced expression or re-expression of TSGs, suppresses cell growth and induces apoptosis." (PMID 21496237, 2011). "UHRF1 is essential for cell proliferation and therefore, to our opinion it would be more rational to target cancer types in which UHRF1 is actually found in high abundance, i.e., over-expressed." (PMID 21496237, 2011).
cancer (continued). "Targeting UHRF1 abundance and/or UHRF1's enzymatic activity would have application in several types of cancer." (PMID 21496237, 2011). "This suggests that these chemo-preventive and chemotherapeutic compounds potentially have the virtues to repair the "wrong" epigenetic code in cancer cells by targeting the epigenetic integrator UHRF1." (PMID 21496237, 2011). "UHRF1 has been reported to be over-expressed in various cancers such as breast, bladder, kidney, lung, prostate, cervical, and pancreatic cancers, as well as in astrocytomas and glioblastoma." (PMID 21496237, 2011). "Expression of UHRF1 is upregulated in various cancers, including breast, prostate, lung, astrocytomas, pancreatic cancers, and cervical cancer." (PMID 19491893, 2009). "Knockdown of UHRF1 expression in cancer cells suppressed cell growth significantly, indicating that UHRF1 is essential for progression of cancers." (PMID 19491893, 2009). "Therefore, we conclude that loss of DNA methylation caused by degradation of UHRF1 and/or DNMT1 causes cancer cells to senesce in vivo." (PMID 40595593, 2025). "Moreover, the epigenetic regulator UHRF1 is aberrantly expressed in cancer, where TME signals like TGF‐β induce its phosphorylation and cytoplasmic translocation." (PMID 40673641, 2025). "The consequences of removing UHRF1 from normal cells differ from what we observe in cancer cells." (PMID 40595593, 2025). "Our work identifies domains of UHRF1 that are essential for preventing senescence of cancer cells." (PMID 40595593, 2025). "UHRF1 is overexpressed in several cancer types, including lung and breast cancers." (PMID 40002221, 2025). "One possible mechanism related to DNMT1/UHRF1 upregulation, leading to cancers, could be disturbed DNMT1 function due to post-translational modifications, leading to aberrant methylation activity." (PMID 40558829, 2025). "Lastly, we have carried out our experiments in human cancer cells, but it will be worthwhile in the future to clarify whether UHRF1 also promotes DNMT3A/DNMT3B activity in other systems, such as mouse embryonic stem cells." (PMID 38580649, 2024). "This intricate interplay between UHRF1, BRCA1, and auxiliary factors underscores their significant contributions to DNA repair processes and gene regulation, positioning UHRF1 as a key player in the maintenance of genomic integrity and the prevention of diseases, particularly cancer." (PMID 39051184, 2024). "The next section underscores UHRF1’s roles across several hallmarks of cancer, including promoting cell proliferation, avoiding cell death, inducing angiogenesis and metastasis, contributing to drug resistance, and the epigenetic silencing of tumor suppressor genes." (PMID 39051184, 2024). "Therefore, the questions we address in this paper are: how does UHRF1 control DNA methylation in human cancer cells?" (PMID 38580649, 2024). "Several studies indicate that cancers overexpressing UHRF1 can evade programmed cell death." (PMID 39051184, 2024). "Recent studies have indicated that UHRF1 plays essential role in the development of cancer cells." (PMID 39709438, 2024). "The nuanced understanding of UHRF1’s role across different cancers posits a roadmap for developing targeted therapies that could revolutionize cancer treatment." (PMID 39051184, 2024). "We hypothesize that UHRF1 dysfunction (specifically to the ubiquitination axis) contributes to the formation of PMDs in ageing and cancer." (PMID 39607687, 2024).
cancer (continued). "Therefore, while the overexpression of UHRF1 can help cancer cells evade apoptosis, the effect of reducing UHRF1 on cell death depends on the type of cancer." (PMID 39051184, 2024). "Additionally, aberrant overexpression of UHRF1 has been observed in over ten cancer types, indicating that UHRF1 is a typical oncogene." (PMID 38725075, 2024). "Therefore, UHRF1 is a key regulator of the cancer epigenome, and it is important to elucidate its role, both for basic research and for medical purposes." (PMID 38580649, 2024). "Additionally, HSP90 inhibitors have been reported to induce UHRF1 ubiquitination-mediated protein degradation, thereby inhibiting cancer cell proliferation." (PMID 38725075, 2024). "Finally, the downregulation of various regulatory mi-RNAs leads to a high-level expression of UHRF1 proteins in cancers." (PMID 37630248, 2023). "Moreover, we further validated that PLK1-induced UHRF1 phosphorylation and protein stability is required for the silencing of TSGs and sustaining cell viability for cancer cells." (PMID 37788997, 2023). "Moreover, the activity of CD47 (cluster of differentiation 47) integrins increases UHRF1 expression in different cancers and represses the activity of many tumor-suppressor proteins." (PMID 37630248, 2023). "The levels of UHRF1 have been found to be upregulated in many cancers." (PMID 37630248, 2023). "Nevertheless, the efficiency of the drug might depend on the level of UHRF1 found in each type of cancer." (PMID 37630248, 2023). "Further development of DSG derivatives with improved affinity for UHRF1 and inhibitory action on UHRF1 activity could lead to a promising strategy against cancer." (PMID 37630248, 2023). "In different types of cancers, the expression of UHRF1 incurs many changes getting out of control." (PMID 37810976, 2023). "UHRF1 deficiency can enhance the migratory and invasive properties of cells via inducing EMT, increasing the tumorigenic capacity of cells and leading to the expansion of cancer stem-like cells." (PMID 36941989, 2023). "UHRF1 is an oncogene that was overexpressed in many cancers and promotes cancer progression." (PMID 36712589, 2023). "Studies have shown that UHRF1 is an oncogene promoting cancer cell development." (PMID 37810976, 2023). "In addition, further investigations are also needed to fully assess the exact mechanism by which these natural drugs or synthetic compounds reverse the effect of UHRF1 overexpression in cancer." (PMID 37630248, 2023). "In addition, 13 UBRs were deregulated in 20 or more cancer types, of which UHRF1 and UBE2C were both deregulated in 25 cancer types." (PMID 37667177, 2023). "Recent studies suggest that downregulation of UHRF1 in cancer cells generates oxidative stress, and it is possible that the high levels of UHRF1 overexpression in this zebrafish model and in precancer cells exerts a dominant negative effect to suppress anti-oxidant defenses." (PMID 37190230, 2023). "However, since luteolin also down-regulates UHRF1 (see later), it is unlikely that its primary mechanism of action in terms of anti-cancer properties is related to the binding to SRA." (PMID 37630248, 2023). "DMR on the UHRF1 was most highly methylated in carcinoma, followed by benign." (PMID 37460953, 2023). "Therefore, our study elucidates the potential role of UHRF1 in tumor immunity and its use as a prognostic biomarker for cancer." (PMID 35656341, 2022). "Indeed, besides being a regulator of DNA maintenance methylation, UHRF1 is involved in several biological processes such as embryogenesis, cell migration, proliferation as well as tumor development and cancer metastasis." (PMID 36060265, 2022). "Taken together, these facts suggest that UHRF1 is not only a marker of immune invasion and poor prognosis but also that its methylation may be a candidate and promising therapeutic target for cancer." (PMID 35656341, 2022). "UHRF1 has become an important prognostic biomarker and a vital cancer therapeutic target." (PMID 35996525, 2022).
cancer (continued). "We speculate that UHRF1 may be a novel target for cancer therapy, as it is upregulated in a variety of cancers and is associated with poorer prognosis." (PMID 35656341, 2022). "Therefore, it is necessary to investigate the expression survival prognosis of cancers with abnormal expression of UHRF1 immune infiltrates in DNA methylation and functional pathways." (PMID 35656341, 2022). "UHRF1 protein is also found to be highly expressed in cancer cells across the cell cycle." (PMID 35991572, 2022). "However, small inhibitors targeting UHRF1, promote the sensitivity of therapeutics and elevate cancer inhibition." (PMID 35991572, 2022). "While UHRF1 is necessary for survival, is its dysfunction sufficient to promote cancer?" (PMID 35625988, 2022). "The present study showed that BSO decreased the expression of UHRF1 in a panel of cancer cells." (PMID 35566130, 2022). "The association between UHRF1 expression and TMB MIS differed significantly between cancer types." (PMID 35656341, 2022). "UHRF1 is overexpressed in many cancers, possibly because it is an S-phase marker." (PMID 35625988, 2022). "UHRF1 is an appealing target for drug design, as it contains several druggable protein binding domains, along with a catalytic activity that is essential for the survival of cancer cells." (PMID 35625988, 2022). "UHRF1 suppression also prevents cell proliferation by inducing cell cycle arrest and apoptosis through DNA demethylation, which suggests that UHRF1 could be a potential biomarker and therapeutic target for cancer diagnosis and treatment." (PMID 36060265, 2022). "Thus, targeting the UHRF1-mediated epigenetic machinery is considered a promising approach to change the altered epigenetic state in cancer cells and allowing the re-expression of TSGs." (PMID 35566130, 2022). "Several studies have revealed that UHRF1 was an oncogene and could promote the development of cancer cells." (PMID 35996525, 2022). "In the context of HCC, the overexpression of UHRF1 promotes tumorigenesis and cancer progression." (PMID 35345849, 2022). "BSO-induced UHRF1’s downregulation in cancer cells could be in large part attributed to the high content of thymoquinone in BSO." (PMID 35566130, 2022). "Thus, we evaluated a novel role of UHRF1 in cancer cell induction of endothelial cell migration (sprouting) using a fibrin gel bead assay." (PMID 36068209, 2022). "However, UHRF1 regulation is complex in cancer, and likely the candidates we identify here will have a role in regulating UHRF1 activity in the cancer context too." (PMID 35324392, 2022). "A comprehensive analysis of UHRF1 in 33 cancers was performed based on TCGA database." (PMID 35656341, 2022). "Interestingly, UHRF1 was indicated as a universal cancer biomarker, while GCSH seems to be newly observed." (PMID 34204789, 2021). "UHRF1 is highly expressed in many types of cancers and is an oncogene in the liver." (PMID 34356097, 2021). "The UHRF1 protein is essential for cell proliferation and is overexpressed in rapidly multiplying cancer cells; therefore, one possibility is that normally growing cells are less sensitive to TQ than their cancer cell counterparts that have high expression of UHRF1." (PMID 33922029, 2021). "However, a later study showed that UHRF1 is also subjected to methylation-mediated protein degradation, and that LSD1 regulates UHRF1 protein stability in cancer cells." (PMID 34831474, 2021). "UHRF1 is a potential driver gene that promotes aberrant DNA hyper-methylation in cancer cells." (PMID 33658396, 2021). "However, despite this seemingly critical function of the TTD, in mouse ES cells, and in human cancer lines, a mutant version of UHRF1 with an inactivated TTD can almost fully substitute for the wild-type protein to ensure steady-state DNA methylation levels." (PMID 33300031, 2021).